RSAD2 (radical S-adenosyl methionine domain containing 2)
Diseases named in the same sentence as RSAD2 in open-access papers (continued):
Sharing a sentence is not in itself a finding about the gene and the disease.
oral cancer (2 papers, 2022 to 2024). "The Cancer Genome Atlas (TCGA) gene expression profile and Kaplan–Meier analysis revealed that high expression of radical s‐adenosyl methionine domain containing 2 (RSAD2) in patients with oral cancer was associated with a better prognosis." (PMID 39233332, 2024). "Albeit, some studies have shown the anti‐tumour role of RSAD2 in lung and oral cancers." (PMID 35810383, 2022).
parasite infection (2 papers, 2022 to 2023). "However, the specific interactions between RSAD2 and parasites and the extent of its influence on parasitic infections require further investigation." (PMID 38179044, 2023).
pemphigus (2 papers, 2017 to 2022). Pemphigus is a group of rare autoimmune diseases that cause blistering of the skin and mucous membranes (mouth, nose, throat, eyes, and genitals).This conditioncan occur at any age, but often strikes people in middle or older age. "Although it has been previously demonstrated that Th2 cells exert broad activity in blister formation in pemphigus, the association of RSAD2 with pemphigus is unknown." (PMID 29387060, 2017).
thrombosis (2 papers, 2024). "However, the presence and extent of recurrence of thrombosis were positively associated with the expression of IFI44, OAS1, and RSAD2 as well as with the IFN score in patients with SAPS." (PMID 38550580, 2024). "Significantly upregulated RSAD2 is involved in the process of spinal cord injury and is associated with the staging, grading, and lymphatic metastasis of malignant tumors, while SLC44A2 is associated with ventricular tachycardia and the formation of venous thrombosis." (PMID 38891594, 2024).
age-related macular degeneration (1 paper, 2019). Age-related loss of vision in the central portion of the retina (macula), secondary to retinal degeneration. "In another study, treatment of retinal pigment epithelium (RPE) cells with amyloid-β1-40, a known inflammatory trigger in Age-related macular degeneration (AMD) caused a significant induction of inflammatory genes such as BST2, STAT1, RSAD2, MX2, OAS1&2, IFNL44 and LXN43." (PMID 30914656, 2019).
allergic asthma (1 paper, 2022). A asthma with a basis in a pathological type I hypersensitivity reaction. "MX1, RSAD2, IFIT1, IFI27, OAS3, and SAMD9L were markedly elevated in HDM-treated mice and positively associated with IL-5, IL-13 and MUC5AC (key mediators of allergic asthma)." (PMID 36211429, 2022). "Furthermore, MX1, RSAD2, IFIT1, IFI27, OAS3, and SAMD9L levels correlated positively with IL-5, IL-13, and MUC5AC levels, which are the key mediators of allergic asthma." (PMID 36211429, 2022).
Alzheimer disease (1 paper, 2020). A progressive, neurodegenerative disease characterized by loss of function and death of nerve cells in several areas of the brain leading to loss of cognitive function such as memory and language. "Interestingly, cell cycle dysregulation was recently identified in single cell RNA-seq analysis of microglia from a mouse model of Alzheimer’s disease (AD), with some of the same genes identified in our study, including Top2a, Hells, Ccne1, Spc25, Cenpe, Anln, Rsad2, and Ifitm335." (PMID 32792571, 2020).
Atherosclerotic lesion (1 paper, 2024). A lesion associated with atherosclerosis, a multifactorial and multipart progressive disease manifested by the focal development within the arterial wall of lesions, that ranges from the development of a fatty streak, plaque progression, and plaque disruption. "Due to high abundance of SMCs in human carotid atherosclerotic lesions and the fact that these cells express RSAD2 in human carotid lesions, we sought to further study the function of RSAD2 in cultured hAoSMCs." (PMID 38589444, 2024).
cervical cancer (1 paper, 2025). A primary or metastatic malignant neoplasm involving the cervix. "The survival analysis from the TCGA database further emphasizes the clinical relevance of this study, showing that lower RSAD2 expression is associated with worse cervical cancer prognosis." (PMID 40510586, 2025). "Notably, lower RSAD2 expression appeared to be linked to worse cervical cancer prognosis, while low IFIT1 expression was also associated with poorer survival, though its predictive power was not statistically significant (p > 0.05)." (PMID 40510586, 2025). "In the cervical cancer vs. normal tissue groups, RSAD2 and IFIT1 expression was significantly upregulated in macrophages and T cells, with additional expression observed in epithelial cells and proliferative cells." (PMID 40510586, 2025). "Our research further confirms the critical role of RSAD2 in the progression of cervical cancer, suggesting it as a potential new target for cervical cancer prevention and treatment." (PMID 40510586, 2025). "In contrast, in cervical cancer tissues, both RSAD2 and IFIT1 were markedly elevated in macrophages, and RSAD2 was significantly downregulated in fibroblasts." (PMID 40510586, 2025). "Our findings support the hypothesis that RSAD2 could serve as a prognostic biomarker and a potential therapeutic target for cervical cancer." (PMID 40510586, 2025). "Notably, RSAD2 expression was significantly increased in macrophages and T cells in cervical cancer tissues, which may reflect changes in the tumor immune microenvironment." (PMID 40510586, 2025). "Moreover, single-cell transcriptomic data analysis in this study revealed the dynamic expression patterns of RSAD2 and IFIT1 across different cell types, particularly during HPV infection and cervical cancer progression." (PMID 40510586, 2025). "Notably, single-cell transcriptomics revealed distinct RSAD2 and IFIT1 expression patterns in immune and epithelial cells during the progression from HPV infection to cervical cancer." (PMID 40510586, 2025). "The observed upregulation of RSAD2 in immune cells, particularly macrophages, may represent an adaptive immune response to persistent HPV infection and chronic inflammation—both of which are hallmarks of cervical cancer progression." (PMID 40510586, 2025). "However, in cervical cancer tissues IFIT1 expression was significantly upregulated, while RSAD2 showed no notable change." (PMID 40510586, 2025).
cholangiocarcinoma (1 paper, 2025). A carcinoma that arises from the intrahepatic biliary tree (intrahepatic cholangiocarcinoma) or from the junction, or adjacent to the junction, of the right and left hepatic ducts (hilar cholangiocarcinoma). "Studies have shown that RSAD2 inhibits the proliferation and metastasis of cholangiocarcinoma (CCA) cells, suggesting that it influences tumor progression through the regulation of energy metabolism." (PMID 40430829, 2025).
depression (1 paper, 2025). "Regardless of the timepoint of sample collection (pregnancy or postpartum), both ISG15 and RSAD2 were upregulated in the group with postpartum-onset depression compared to the controls (logFC 0.6–0.8, and 1.1 respectively)." (PMID 40473930, 2025).
disc degeneration (1 paper, 2022). "However, within these processes, only a few genes were commonly upregulated in human cluster D2 and N153S tissues, including BIRC3, CFD, RSAD2, and ALCAM – none of which are considered inflammatory hallmarks of disc degeneration." (PMID 35769461, 2022).
endometrial adenocarcinoma (1 paper, 2023). "Similarly, both kaempferol and progesterone treatment downregulated RSAD2 which is both upregulated and associated with poorer progression in patients with endometrial adenocarcinoma." (PMID 36986136, 2023).
gastric cancer (1 paper, 2025). A primary or metastatic malignant neoplasm involving the stomach. "On the other hand, RSAD2 upregulation has been reported to confer poor prognosis in breast and gastric cancers." (PMID 41439936, 2025). "In particular, RSAD2 was reported to be an adverse prognostic factor in breast and gastric cancers but a favorable prognostic factor in oral cancer and melanoma." (PMID 41439936, 2025). "Furthermore, RSAD2 gene upregulation has been reported to be associated with poor survival in patients with breast and stomach cancer, but its prognostic value in HCC has not been formally evaluated." (PMID 41439936, 2025).
heart failure (1 paper, 2024). Inability of the heart to pump blood at an adequate rate to meet tissue metabolic requirements. "Another study screened key genes linked to mitochondrial function in heart failure, including the IFN-related genes RSAD2 and MX1, which exhibited substantial enrichment in myogenesis and hypoxia processes." (PMID 38753730, 2024).
Hypertension (1 paper, 2024). The presence of chronic increased pressure in the systemic arterial system. "Even more surprisingly, it has been reported that hypertension is associated with elevated RSAD2 expression in peripheral blood mononuclear cells of systemic sclerosis patients." (PMID 38589444, 2024).
interstitial lung disease (1 paper, 2016). A diverse group of lung diseases that affect the lung parenchyma. "A number of genes, such as Bst2, Rsad2, Ifi44, Oas2 and Stat2, were previously found to be downregulated in pulmonary fibroblasts from IPF patients and from scleroderma-associated interstitial lung disease." (PMID 27428020, 2016).
lung carcinoma (1 paper, 2022). "Human lung cancer NCI‐H358 (H358) cells showed significant up‐regulation of DDX58, MDA5, MAVS, IRF7, IFNB, RSAD2, and ISG56, after incubation with immRNA‐loaded RBCEVs." (PMID 35430766, 2022).
metastatic disease (1 paper, 2025). "However, clinical research on RSAD2 in HCC is lacking, and it is of clinical interest whether RSAD2 has an association with metastatic disease." (PMID 41439936, 2025).
ovarian tumor (1 paper, 2022). "qRT-PCR analyses revealed that STINGPOX drives RSAD2 and IFNB1 expression in the ovarian tumor explants, consistent with our in vitro observations in cancer cell lines." (PMID 36713447, 2022).
Peri-Implantitis (1 paper, 2025). An inflammatory process with loss of supporting bone in the tissues surrounding functioning DENTAL IMPLANTS. "NRIR promotes NF-κB activation through RSAD2, reduces osteogenesis-related factors in BMSCs, and promotes inflammation-induced bone resorption in peri-implantitis." (PMID 41190073, 2025). "In summary, this study elucidates the NRIR/RSAD2/NF-κB pathway regulating M1 macrophage activation, suggesting potential therapeutic targets for peri-implantitis prevention and treatment." (PMID 41190073, 2025). "This study demonstrates that NRIR functions as a pro-inflammatory modulator in peri-implantitis by activating M1 macrophages through the RSAD2/NF-κB axis, providing novel insights into peri-implantitis pathogenesis that may inform future preventive and therapeutic strategies." (PMID 41190073, 2025).
Rotavirus infection (1 paper, 2017). Infection with any of the rotaviruses. "Of interest, several IFN inducible genes (OAS1, MX1, IL18, IITP3, TAP1, and RSAD2) as well as several cytokines and chemokines (CCL5, CXCL10, CXCL11, IL8, and CCL15) were upregulated by rotavirus infection." (PMID 28210256, 2017).
Thrombocytopenia (1 paper, 2022). A reduction in the number of circulating thrombocytes. "We found that SLE patients with thrombocytopenia had considerably lower expression levels of NRIR, RSAD2, and IFI44 than SLE patients with normal platelet counts." (PMID 35967341, 2022).
triple-negative breast carcinoma (1 paper, 2024). An invasive breast carcinoma which is negative for expression of estrogen receptor (ER), progesterone receptor (PR), and human epidermal growth factor receptor 2 (HER2). "RSAD2 has also been identified as a prognostic predictor in triple-negative breast cancer, but the exact mechanism remains unclear." (PMID 38549776, 2024).
type 1 diabetes (1 paper, 2020). "Transcript analyses in human islets indicate that expression of several genes connected to antiviral response increases including IFIH1 (well established type 1 diabetes risk gene) and RSAD2 in virus infected islet cells." (PMID 33154504, 2020).
infection (111 papers, 2011 to 2026). The state of being infected such as from the introduction of a foreign agent such as serum, vaccine, antigenic substance or organism. "For example, research has shown increased RSAD2 expression in response to infections caused by protozoan parasites like Toxoplasma gondii and Plasmodium falciparum, respectively." (PMID 38179044, 2023). "We also detected a high IFNβ and antiviral RSAD2 upregulation 1 day after infection with the chimera virus in four out of five mice." (PMID 40827915, 2025). "To evaluate the diagnostic accuracy of two hub genes, RSAD2 and IFIT1, in predicting infection status, we performed ROC analysis on HPV16-infected and GV-infected samples across different datasets." (PMID 40510586, 2025). "Immune response genes such as the pro-inflammatory cytokine CXCL10, IFI27, USP18, IFIT1, and RSAD2/Viperin were shared between both in vivo infection times and A549 cells." (PMID 39065267, 2024). "Some viruses induce the upregulation of both RSAD2 mRNA and protein expression during infection, but their antiviral activity is impaired." (PMID 39334325, 2024). "For example, the up-regulation of RSAD2 in Mycobacterium tuberculosis hinders host defense activation and antigen presentation in dendritic cells during infection with this pathogen." (PMID 38673764, 2024). "In contrast, Rsad2 shows similar expression levels for both viruses at both 24 h and 72 h post-infection." (PMID 39205301, 2024). "In conclusion, we demonstrated that SVA infection blocks the antiviral activity of RSAD2 by reducing RSAD2 expression." (PMID 39334325, 2024). "Overexpression of the porcine radical S-adenosyl methionine domain containing 2 (RSAD2) gene inhibited the replication of the CSF virus and reduced the infection in vitro." (PMID 39684818, 2024). "Our results displayed some proteins (IRG1, GBP5, PDL1, and ICAM1) correlated in all the conditions forming a unique section, in combination with other proteins in each specific condition, such as RSAD2, presented only in the Y infections." (PMID 39000601, 2024). "In individuals affected by influenza virus infection, IFFI44L, ISG15, IFIT3, and RSAD2 are crucial antiviral factors inhibiting infection within alveolar basal epithelial cells." (PMID 38601162, 2024). "Independently of SLAMF1, with the Y strain infection, there was one common upregulated protein, the radical S-adenosyl methionine domain containing 2 (RSAD2), and with the VFRA strain there was one common downregulated protein, the phospholipase D3 (PLD3)." (PMID 39000601, 2024). "Upon infection, RSAD2-expressing neutrophils significantly increased in both sexes in the blood (***p < 0.001) and the liver (*p< 0.05 (males); ***p < 0.001 (females))." (PMID 38179044, 2023). "Neutrophils from females showed higher protein expression of the type I ISG viperin/RSAD2 during infection, which decreased by testosterone substitution." (PMID 38179044, 2023). "Both serum IFNβ and hepatic IFNβ-dependent genes (including Ifit2, Rsad2, Iigp1 and many more of the ISGs discussed here) were over-expressed in Dusp1-/- mice following infection with E. coli." (PMID 37942320, 2023). "After 48 h of infection, immunofluorescent staining showed that the RSAD2 protein expression was enhanced in keratinocytes treated with LL-37 and hBD-3, whatever the concentration of the peptide used." (PMID 35891533, 2022). "The expression heatmaps of the endothelial cell genes in the sample revealed that DCN and IFN-activated endothelial cell marker genes (Irf8, Rsad2, Ifit1, Ifit3, Iigp1) were significantly upregulated at 1 month post-infection as compared with the WT group." (PMID 36569953, 2022). "Vaginal tissue from mice infected locally with HSV-2 showed strong RSAD2 expression in cells located to the area of infection." (PMID 35646147, 2022). "Compared with the sh-control cells, RSAD2 knockdown promoted both the mRNA and protein expression of the influenza virus NP gene during infection." (PMID 36423196, 2022).
infection (continued). "IFI44, ISG15, MX1, RSAD2, SAMD9 and TNFSF10 were chosen as they are infection-associated genes that show lower expression levels in Holstein infected cells compared to Sahiwal cells." (PMID 35061738, 2022). "ISG expression, quantified by Rsad2 mRNA expression, was significantly induced in the lungs and spleen seven days post-infection." (PMID 36558888, 2022). "The present study showed that IFN-λ was more dominantly induced in the lung of SARS-CoV-2-infected hamsters from an early stage of infection and mediated the induction of ISGs such as Mx1, Rsad2, and IFIT3 preferentially from 3 dpi." (PMID 36524125, 2022). "ISGs and immune response genes such as IFIT1, IFIT2, IFIH1, MX1, MX2, and RSAD2 were highly down-regulated in response to all viruses at later time points of infection, confirming our transcriptome data." (PMID 33791243, 2021). "Genes encoding interferons (Ifnb, Ifnl2 and Ifnl3), chemokines (Ccl7, Ccl5, and Cxcl10), and ISGs (Ifit1, Ifit2, Ifit3b, Oas3, Ifi44, Rsad2, and Isg15, among others) were prominently represented among those induced by infection in Ifnar1-/- mice." (PMID 34591933, 2021). "Some interferon stimulated genes such as OAS1, OAS3, MX1, and RSAD2 that were strongly induced by rDEN2Δ30 infection are also known to be regulated in natural infection." (PMID 34031380, 2021). "The expression of Radical S-Adenosyl Methionine Domain Containing (rsad) 2 gene, also known as VIPERIN, was sustained in all infection groups, but with a higher induction pattern seen in probiotics-supplemented groups." (PMID 33172079, 2020). "DKO cells were confirmed to show minimal induction of IFNs (Ifnα4) and IFN-induced gene Rsad2 following 12 hours of infection by either T3DPL or T3DTD." (PMID 32956403, 2020). "The up-regulated TF ZFHX3 targets seven genes in module AD_M25, where two genes OAS1 and RSAD2 are detected in infection pathways, and the other five genes FAM122B, SAMD9, TRIM21, USP18 and IFIT3 are also known to be related to infectious disease." (PMID 30598117, 2018). "The genes OAS1 and RSAD2 play important roles in infection pathway, imposing an activation effect on several infectious disease response pathways detected in AD compared to normal samples." (PMID 30598117, 2018). "Among the genes associated with responses to virus, TLR3, IRF1, GATA3, SAMHD1 and RSAD2 were all significantly up-regulated on both day 1 and day 3 post infection." (PMID 28486945, 2017). "We show that infection with live bacilli specifically alters the expression of host genes such as Rsad2, Ifit1/2/3 and Rig-I, whose potential roles in resistance to M. tuberculosis infection have not yet been investigated." (PMID 28176867, 2017). "We observed similar findings with RSAD2 expression, with PR-1966 infection inducing lower transcript levels at 12hpi, but increased responses at 24hpi as compared to PR-2015." (PMID 28152048, 2017). "We found that infection with the IFN-sensitive RRV strain resulted in the robust induction of several well-defined ISGs, including those encoding IFIT1/2/3, ISG15, ISG20, RSAD2, and Mx2." (PMID 27128797, 2016). "It is important to note that some viruses, such as human cytomegalovirus (HCMV), have been shown to use specific ISGs, such as RSAD2, to enhance infection." (PMID 27608486, 2016). "Nod1 (C10) and its responsive genes Irf7 and Stat1 (C11) were elevated late during infection as well as interferon-induced genes Cxcl10, Ifit1-3, Iigp1 and Rsad2 (C7)." (PMID 26367386, 2015). "EBV primary infection and reactivation lead to a coordinated upregulation of RSAD2 and CMPK2." (PMID 41676616, 2026). "Protein–protein interaction network analysis identified several hub genes (Usp18, Stat2, Ifih1, Jun, Irf7, Rsad2, Ifit1, Mx1) that likely play central roles in coordinating the antiviral immune response and immunometabolic regulation across different phases of infection." (PMID 40867782, 2025).